CHKA (choline kinase alpha)
Diseases named in the same sentence as CHKA in open-access papers (continued):
Sharing a sentence is not in itself a finding about the gene and the disease.
rheumatoid arthritis (1 paper, 2024). A chronic, systemic autoimmune disorder characterized by inflammation in the synovial membranes and articular surfaces. "Choline kinase alpha (ChoKα) is a therapeutic target being developed for a variety of diseases, from cancer to rheumatoid arthritis and from parasites to bacterial infections." (PMID 39568820, 2024).
spina bifida (1 paper, 2006). A congenital neural tube defect in which vertebrae are not fully formed. "Effect estimates (odds ratios) for spina bifida-affected pregnancies associated with CHKA SNPs hCV1562388 (A>C) and hCV1562393(C>G), PCYT1A SNPs rs939883 (T>A) and rs3772109 (T>C), California 1989–1991." (PMID 17184542, 2006). "Given that periconceptional intake of choline has been associated with decreased risk of NTD-affected pregnancies, we investigated CHKA and PCYT1A genotypes on risk of spina bifida." (PMID 17184542, 2006). "Reduced risks of spina bifida were found for CHKA SNP hCV1562388, and increased risks were found for SNP rs939883." (PMID 17184542, 2006). "Despite its limitations, this study provided initial data indicating a potential association between CHKA and PCYT1A gene variants and spina bifida risk." (PMID 17184542, 2006). "This study investigated whether single nucleotide polymorphisms (SNPs) in human choline kinase A (CHKA) gene and CTP:phosphocholine cytidylytransferase (PCYT1A) gene were risk factors for spina bifida." (PMID 17184542, 2006). "Future studies of additional SNPs within the CHKA and PCYT1A genes should be investigated as potential predictors of spina bifida risks." (PMID 17184542, 2006).
cancer (50 papers, 2009 to 2025). A tumor composed of atypical neoplastic, often pleomorphic cells that invade other tissues. "Choline kinase alpha (CHKA) is a central mediator of cell metabolism linked to cancer and immune regulation." (PMID 39740997, 2025). "CHKA has been extensively studied in the fields of cancers, where it is implicated in promoting tumor cell proliferation, migration, and survival." (PMID 40548950, 2025). "Malignant transformation is characterised by aberrant phospholipid metabolism of cancers, associated with the upregulation of choline kinase alpha (CHKα)." (PMID 38138508, 2023). "A wide range of cancers exhibits phosphatidylcholine metabolism alterations, caused mainly by choline kinase alpha (CHKA), phospholipase C (PLC) or phospholipase D (PLD) enhanced activity." (PMID 32715369, 2020). "CHKA, known to be overexpressed in a variety of cancers and associated with the PI3K/AKT signaling pathway 18, 19, was found to be downregulated after CQ treatment, leading to a significant reduction in PI3K and AKT phosphorylation and tumor cell proliferation." (PMID 39990656, 2025). "To obtain information on genetic alterations of choline kinase in human cancers, we searched the Cancer Genome Atlas (TCGA) for the presence and frequency of gene amplification, deletion and mutation on CHKA and CHKB in various human lymphoid malignancies as compared to solid tumors." (PMID 34202989, 2021). "The cardinal enzyme of choline metabolism, choline kinase alpha (CHKα), has been described as the main regulator of the cholinic phenotype and could be associated with tumor progression in various cancers." (PMID 27705917, 2016). "Altered PC metabolism is linked to various cancers, driven by specific enzyme activities such as choline kinase alpha and phospholipases C and D. Variations in PC levels can affect cell proliferation and energy metabolism in cancer cells." (PMID 40733051, 2025). "It is reported that PCho, the direct metabolite of CHKA, is abnormally elevated in various cancers and is able to provide phosphate molecules for AKT activation, thus promoting tumor proliferation." (PMID 36147318, 2022). "On the other hand, the inhibition of cell signaling (e.g., PI3K) inhibits expression of CHKA, highlighting the role of choline kinase in cancer cell transduction and oncogenic metabolic reprogramming (and see references therein)." (PMID 35740569, 2022). "Choline kinase (CHKA) is the first enzyme in the CDP-choline pathway for the synthesis of phosphatidylcholine, Inhibition of CHKA activity has been proposed as a target for cancer therapies and miR-876-5p transfection decreased CHKA in HepG2 cells." (PMID 34001947, 2021). "The transcription of three genes associated with cancer, CDKN1A, SGK1 and CHKA, were measured using qRT-PCR." (PMID 32910239, 2021). "Analysis of the eligible samples revealed that recurrent patients show high values for all the variables associated with the severity of cancer and exhibit high expression levels for ME3, PDK3, CHKA, and MALAT1 transcripts." (PMID 33375130, 2020). "EGFR has been shown to activate the choline kinase-alpha or phosphatidylcholine-specific phospholipase C in some cancer models." (PMID 29983881, 2018). "Further studies are needed to validate the robustness of our findings before clinical translation and provide a better insight into the molecular events involved in the CHKA-facilitated cancer progression and metastasis." (PMID 27556502, 2016). "A number of studies have documented the overexpression of CHKA protein in multiple cancer types including breast, colorectal, endometrial, lung, ovarian, and prostate." (PMID 26657335, 2016). "Consistently, pharmacological inhibitors of CHKA has also displayed antiproliferative, proapoptotic and antitumoral effects against multiple tumor-derived cancer cells as well as tumor xenografts." (PMID 27556502, 2016).
cancer (continued). "Choline kinase alpha is typically overexpressed in cancer and is viewed as playing a central role in mediating the increase in PC levels that is observed in most tumors when compared to normal tissue." (PMID 25706986, 2015). "Hexokinase-2 (HK2) and more recently choline kinase alpha (CKA) expression has been correlated with clinical outcomes in several major cancers." (PMID 23071593, 2012). "The overexpression of choline kinase alpha (CKA) in many cancers has also generated interest in phospholipid metabolism as a diagnostic or therapeutic target in oncology." (PMID 23071593, 2012). "Therefore, the upregulation of CHK activity in cancer probably results from an increase in CHKA expression, which would lead to a higher proportion of CHKA-]–CHKA dimers exerting a higher CHK activity level than CHKA–CHKB heterodimers or CHKB–CHKB homodimers." (PMID 35740569, 2022). "Moreover, it has been demonstrated that inhibition of CHKA can reduce the motility and invasive ability of cancer cells." (PMID 34564442, 2021). "In addition to its metabolic function, CHKA has been proven to play a critical role in tumorigenesis, cancer progression and metastasis of several cancers, establishing it as an oncogene." (PMID 27556502, 2016). "Knockdown of CHKA by RNAi has been demonstrated to induce differentiation and reduce proliferation, prevent mitotic entry, selectively trigger cancer cell apoptosis, suppress migration and invasion, and sensitize cancer cells to chemotherapeutics." (PMID 27556502, 2016). "We have shown that the decrease in PC following treatment with PI-103 is associated with a reduction in the protein expression level of CHKA, the enzyme responsible for phosphorylation of choline into PC, confirming our previous findings in other cancer models." (PMID 25084455, 2014). "Furthermore, it has been shown that CHKA is upregulated in several cancers, and that CHKA expression correlates with PCho concentration in vitro." (PMID 24447408, 2014). "CHKA is an enzyme involved in the metabolism of phospholipids which has been found to play a role in the regulation of cell proliferation, oncogenic transformation and human carcinogenesis, and has been ascertained as a promising target for cancer therapy." (PMID 24025726, 2013). "CHKA is known to play an important role in malignant transformation in several types of cancer." (PMID 22277092, 2012). "Co‐crystal structures of UNC0638 and UNC0737 with CHKA unravel an unexpected binding mode and suggest the inhibitors as attractive starting points for the development of selective chemical tools to further explore the biological role of CHKA in cancer and immune metabolism." (PMID 39740997, 2025). "Furthermore, we performed the molecular docking simulation to screen the potential anti-cancer compounds from dandelion extract, which could exert its pharmacological effects by binding CHKA." (PMID 36147318, 2022). "Furthermore, the interaction between EGFR and CHKA is required for EGF-mediated DNA synthesis and increases proliferation, which may a mechanism by which CHKA promotes oncogenesis in many cancers." (PMID 35326402, 2022). "In addition to PCa, CHKA is oncogenic, and it is known to be upregulated in many cancer types and may, thus, represent an attractive therapeutic target." (PMID 35326402, 2022). "The discovery of a chaperone function of CHKA for AR signaling might also have wider implications in the treatment of other cancers and should accelerate the screening of potential CHKA inhibitors that will not only inhibit the catalytic function but also decrease the CHKA protein level." (PMID 26657335, 2016). "We show that the chaperone function of CHKA confers a growth advantage on PCa by stabilizing the AR in addition to its well-known function in fuelling membrane production through the Kennedy pathway, suggesting a de facto role for CHKA as a rate-limiting factor in cancer cell growth." (PMID 26657335, 2016).
cancer (continued). "Since choline synthesis is a crucial event for cancer cells, MALAT1 targeting downregulates CHKA and CERK activity; this effect seems to overlap the activity of CHKA inhibitors." (PMID 36674430, 2023). "The “cholinic phenotype” is referred to as the overexpression of choline kinase alpha (CHKA) and phosphocholine (PCho) levels in different types of cancers, including PCa." (PMID 36674430, 2023). "In our hands, MALAT1 was found to modulate CHKA expression, PCho, and glutathione in PCa cells, revealing a new MALAT1-dependent link between PC biosynthesis and redox balance in cancer cells." (PMID 35740569, 2022). "Upregulation of the metabolic genes (ALDH18A1, CAD, CHKA, POLD4, PSPH, and SQLE) and aberrant expression of cancer-related genes (ALCAM, ITGA6, DDIT3, MAP3K6, and PAK1) were found in mouse fed with high-fat-high-cholesterol similar to human NASH-HCCs." (PMID 31795276, 2019). "We demonstrated for the first time the aberrant expression of cancer-related genes (ALCAM, ITGA6, DDIT3, MAP3K6 and PAK1) and metabolism-related genes (ALDH18A1, CAD, CHKA, POLD4, PSPH, SQLE and CFD) in human NASH-HCCs." (PMID 30367044, 2018). "The function and regulation of the two enzymes choline kinase α (ChKα) and phospholipase D (PLD) has been more widely explored in cancer, but research into other important enzymes in choline metabolism is still at an early stage." (PMID 28083512, 2016). "In this condition, the so-called “cholinic phenotype”, which is characterized by the overexpression of choline kinase alpha (CHKA) and increased phosphocholine (PCho) levels, supports aberrant lipid metabolic pathways typical of different cancers, including PCa." (PMID 35740569, 2022). "1H MRS helps in the detection of increased choline expression and CHKa activity in cancer cells compared to those in non-tumoral cells, making it a potential biomarker to diagnose cancer and a strategy to follow treatment response." (PMID 35250970, 2022). "Targeting mechanisms upon which cancer cells are expected to be dependent (CHKA expression and cellular ROS homeostasis) could explain the differential response of cancer and non-transformed cells to CHKA knockdown." (PMID 27446799, 2016).
tumor (38 papers, 2012 to 2025). "Activation of AKT signaling by ectopic expression of myr-AKT significantly reversed the reduced tumor cell proliferative and invasive capabilities caused by CHKA knockdown." (PMID 27556502, 2016). "Interestingly, CHKA expression is androgen-regulated in cell lines, xenografts, and human tissue and is positively associated with Asim’s tumor stage." (PMID 35740569, 2022). "Choline kinase alpha (ChoKα) overexpression is associated with an aggressive tumor phenotype." (PMID 28157707, 2017). "CHKA expression was shown to be androgen regulated in cell lines, xenografts, and human tissue (log fold change from 6.75 to 6.59, P = .002) and was positively associated with tumor stage." (PMID 26657335, 2016). "We significantly contributed to define the relevance of this hallmark in EOC as well, showing that tumor cells have an increased expression and activation of ChoKα and that transient CHKA silencing affected cell behavior in vitro, hampering the aggressive phenotype." (PMID 25796169, 2015). "In fact all of the significant associations were located in the choline kinase alpha (CHKA) gene, which encodes a protein essential in the phospholipid biosynthesis and may contribute to tumor cell growth." (PMID 24595071, 2014). "CHKA protein expression was frequently increased in PCa (12% positive cases in non-neoplastic [NN] benign prostate compared with 36% positive cases in PCa; P < .001) and showed some evidence of association with Gleason grade (≤ vs 7) and tumor stage (pT2 vs pT3)." (PMID 26657335, 2016). "Next, we evaluated the gene expression of SLC6A8 and CHKA in matched tumor/normal data for 57 AC and 49 SqCC cases from the TCGA consortium." (PMID 40903981, 2025). "We further compared the glycolytic function of Caco2 and Caco2-shCHKA cells and revealed that CHKA knockdown impaired the glycolytic capacity of tumor cells." (PMID 39990656, 2025). "When comparing bulk tumor tissue to matched normal tissue, the increased mRNA expression of the creatine transporter SLC6A8 gene and decreased CHKA expression appeared tumor‐associated." (PMID 40903981, 2025). "Beyond its role in glycolysis, ENO1 also interacts with choline kinase alpha (CHKα), a key enzyme in choline metabolism, stabilizing it and thereby promoting choline phospholipid metabolism and tumor cell proliferation." (PMID 40248198, 2025). "Both ETNK1 and CHKA genes were found to be up-regulated in tumor tissue, but ETNK1 genes also showed elevated expression in lymphoid tissue (Fig. 4f5, f6, g5, g6)." (PMID 37164975, 2023). "High expression of CHKA is associated with a higher tumor grade and poor prognosis of NSCLC, and silencing of CHKA reduces cell proliferation, migration, and invasion capability." (PMID 35159102, 2022). "Inhibition of the gene CHKA, involved in membrane biosynthesis in the context of normal cellular function, has arrested tumor growth in a selection of tumor types, including HB, HCC, breast, lung, and prostate." (PMID 35563821, 2022). "In the present work, we observe that MALAT1 targeting broadly hurts the cholinic phenotype via the downregulation of CHKA and PCho synthesis, with essential consequences on tumor cell proliferation." (PMID 35740569, 2022). "Overexpression of CHKA has been reported in a wide range of solid tumors, and correlates with advanced histological tumor grade, poor prognosis and reduced survival rates in breast and non-small-cell lung cancers." (PMID 34371769, 2021). "A decrease in CHKA, as we appreciated upon MALAT1 depletion, has been reported to cause inhibition of growth of PCa cells, human PCa explants, and tumor xenografts." (PMID 33375130, 2020). "The consistently high expression in a wide variety of tumor types highlights the relevance of CHKA in malignancy and role as a therapeutic target." (PMID 27206796, 2016).
tumor (continued). "CHKA can act as an AR chaperone, providing, to our knowledge, the first evidence for kinases as molecular chaperones, making CHKA both a marker of tumor progression and a potential therapeutic target for PCa." (PMID 26657335, 2016). "The independent prognostic value of CHKA expression based on tumor stage was further evaluated with a Cox multivariate regression model." (PMID 27556502, 2016). "Mice injected with CHKA-depleted cells showed significantly reduced xenograft tumor growth compared with those injected with control cells." (PMID 27556502, 2016). "The average tumor weight was also significantly decreased in the CHKA depletion groups compared with the control group." (PMID 27556502, 2016). "The immunohistochemical data clearly showed that the immunoreactive score (IRS) values of CHKA were significantly higher in tumor tissues (p < 0.01)." (PMID 27556502, 2016). "Here we elucidate the impact of CHKA inhibition on tumor metabolism using the novel and specific inhibitor ICL-CCIC-0019." (PMID 27206796, 2016). "To understand the effect of perturbing CHKA function on tumor growth kinetics, we used the highly aggressive C4-2b luciferase cell line and engineered it to express three distinct CHKA shRNAs (sh#1, sh#2, and sh#3) in a doxycycline-inducible manner." (PMID 26657335, 2016). "Further analysis of the excised tumor xenografts confirmed a tendency towards decreased CHKA levels and clearly decreased AR protein expression in CHKA sh#2 xenografts from mice treated with doxycycline (available online)." (PMID 26657335, 2016). "In the same study, the authors found hypoxic tumor regions to be co-localized with regions of high tCho, which possibly occurred through the up-regulation of CHKA by HiF-1α." (PMID 22277092, 2012). "Notably, the mRNA expression of both SLC6A8 and CHKA matched the corresponding metabolite level in the tumor tissue." (PMID 40903981, 2025). "Nevertheless, these results suggest that CHKA is essential for tumor growth." (PMID 39990656, 2025). "The mechanism by which CHKA activation plays a tumor-promoting role in ATP8B1 knockdown cell lines remains unclear." (PMID 35159102, 2022). "Therefore, CHKA is being pursued as a therapeutic target and prognostic marker in advanced disease for a range of tumor types." (PMID 26657335, 2016). "Taken together, these studies indicate that CHKA activity may be essential for tumor progression and also for the activation of downstream oncogenic signaling pathways." (PMID 27556502, 2016). "Moreover, CHKA expression was significantly upregulated in advanced stage (stage III) CRC tissues compared with early stage (stages I–II) tumor counterparts at both the mRNA and protein levels (all p < 0.05)." (PMID 27556502, 2016). "Inhibition of CHKA repressed the AR transcriptional program including pathways enriched for regulation of protein folding, decreased AR protein levels, and inhibited the growth of PCa cell lines, human PCa explants, and tumor xenografts." (PMID 26657335, 2016). "In conclusion, our results provide the first evidence that CHKA contributes to tumor progression and metastasis and may serve as a novel prognostic biomarker and potential therapeutic target in CRC." (PMID 27556502, 2016). "CHKA is involved in phospholipid biosynthesis and tumor cell growth." (PMID 26892349, 2016). "For instance, upregulation of choline kinase (CHKA) can contribute to phosphocholine accumulation, a metabolic hallmark of aggressive breast tumors; similarly, mutations or overexpressed isocitrate dehydrogenase (IDH) can produce oncometabolites that promote tumor progression." (PMID 40710528, 2025). "In addition to the catalytic effect, CHKA could act as a mediator in regulating cell signaling transduction and promoting tumor initiation and progression." (PMID 36147318, 2022). "CHKA has a key role in phospholipid biosynthesis and may contribute to tumor cell growth." (PMID 33109104, 2020).